HTR3A (5-hydroxytryptamine receptor 3A)
Description:
Forms serotonin (5-hydroxytryptamine/5-HT3)-activated cation-selective channel complexes, which when activated cause fast, depolarizing responses in neurons.
Synonyms: 5-HT3A; 5-HT-3; 5-HT3R; 5HT3R; HTR3
Tractability: Small molecule: an approved drug acts on it; a structure with a bound ligand is known; a high-quality ligand is known; it belongs to a druggable protein family. Antibody: UniProt places it where antibodies can reach, with high confidence; its Gene Ontology location is reachable by antibodies, with high confidence; UniProt predicts a signal peptide or a membrane-spanning region. PROTAC: ubiquitination databases record sites on it; a small molecule that binds it is known.
Target class: 5HT3 receptor; Ion channel; Ligand-gated ion channel
Chemical probes: PD084803
Safety:
Unwanted effects reported when the protein is acted on. In parentheses: how it was acted on, where the effect was seen, and who reports it.
constipation (Bowes et al. (2012): inhibition, endocrine, gastrointestinal; Lynch et al. (2017): inhibition, acute dosing, central nervous system, cardiovascular, gastrointestinal)
dizziness (Bowes et al. (2012): inhibition, endocrine, gastrointestinal; Lynch et al. (2017): inhibition, acute dosing, central nervous system, cardiovascular, gastrointestinal)
abdominal distension (inhibition, acute dosing; central nervous system, cardiovascular, gastrointestinal; source: Lynch et al. (2017))
apnea (activation, acute dosing; central nervous system, cardiovascular, gastrointestinal; source: Lynch et al. (2017))
decreased anxiety (inhibition, acute dosing; central nervous system, cardiovascular, gastrointestinal; source: Lynch et al. (2017))
decreased gastrointestinal transit (inhibition, acute dosing; central nervous system, cardiovascular, gastrointestinal; source: Lynch et al. (2017))
decreased inflammation (inhibition, acute dosing; central nervous system, cardiovascular, gastrointestinal; source: Lynch et al. (2017))
decreased memory (activation, acute dosing; central nervous system, cardiovascular, gastrointestinal; source: Lynch et al. (2017))
decreased pain (inhibition, acute dosing; central nervous system, cardiovascular, gastrointestinal; source: Lynch et al. (2017))
drug abuse/dependence (activation, acute dosing; central nervous system, cardiovascular, gastrointestinal; source: Lynch et al. (2017))
emesis (activation; endocrine, gastrointestinal; source: Bowes et al. (2012))
gastric emptying (activation; endocrine, gastrointestinal; source: Bowes et al. (2012))
hard stool (inhibition, acute dosing; central nervous system, cardiovascular, gastrointestinal; source: Lynch et al. (2017))
hyperglycaemia (activation; endocrine, gastrointestinal; source: Bowes et al. (2012))
increased blood pressure (activation, acute dosing; central nervous system, cardiovascular, gastrointestinal; source: Lynch et al. (2017))
increased gastric emptying (activation, acute dosing; central nervous system, cardiovascular, gastrointestinal; source: Lynch et al. (2017))
increased gastrointestinal transit (activation, acute dosing; central nervous system, cardiovascular, gastrointestinal; source: Lynch et al. (2017))
increased heart rate (activation, acute dosing; central nervous system, cardiovascular, gastrointestinal; source: Lynch et al. (2017))
increased memory (inhibition, acute dosing; central nervous system, cardiovascular, gastrointestinal; source: Lynch et al. (2017))
ischemic colitis (inhibition, acute dosing; central nervous system, cardiovascular, gastrointestinal; source: Lynch et al. (2017))
possible increased heart rate (activation; endocrine, gastrointestinal; source: Bowes et al. (2012))
vomiting (activation, acute dosing; central nervous system, cardiovascular, gastrointestinal; source: Lynch et al. (2017))
Gene: Protein-coding gene on chromosome 11 (113,975,075 to 113,990,313, forward strand). Ensembl gene ENSG00000166736.
Subcellular location: Postsynaptic cell membrane; Cell membrane
Pathways (Reactome):
Neuronal System: Neurotransmitter receptors and postsynaptic signal transmission
Gene Ontology:
Molecular function: protein binding; serotonin binding; serotonin-gated monoatomic cation channel activity; extracellular ligand-gated monoatomic ion channel activity; identical protein binding; ligand-gated monoatomic ion channel activity; ligand-gated monoatomic ion channel activity involved in regulation of presynaptic membrane potential; monoatomic ion channel activity; transmembrane signaling receptor activity
Biological process: serotonin receptor signaling pathway; serotonin-gated cation-selective signaling pathway; transmembrane transport; calcium ion transport; monoatomic ion transmembrane transport; monoatomic ion transport; regulation of presynaptic membrane potential
Cellular component: cleavage furrow; plasma membrane; serotonin-activated cation-selective channel complex; neuron projection; synapse; transmembrane transporter complex; membrane; postsynaptic membrane
Genetic constraint (gnomAD): Loss-of-function variants: 41 observed, 51.43 expected, observed/expected ratio (o/e) 0.8, 90% interval 0.62 to 1.03. The upper end of that interval is the gene's LOEUF score, 1.03, which puts it in group 4 of 6, group 1 being the genes least tolerant of losing a copy. Missense variants: 625 observed, 610.45 expected, observed/expected ratio (o/e) 1.02, 90% interval 0.96 to 1.09. Synonymous variants: 285 observed, 255.3 expected, observed/expected ratio (o/e) 1.12, 90% interval 1.01 to 1.23.
Homologues: Orthologues: chimpanzee HTR3A (99% identical), rabbit HTR3A (88% identical), dog HTR3A (88% identical), pig HTR3A (86% identical), mouse Htr3a (85% identical), rat Htr3a (83% identical), macaque HTR3A (81% identical), guinea pig HTR3A (81% identical), tropical clawed frog HTR3A (64% identical), zebrafish htr3a (58% identical). Paralogues in human: HTR3B (39% identical), HTR3E (33% identical), HTR3C (32% identical), CHRNA4 (27% identical), CHRNA5 (26% identical), CHRNA6 (25% identical), CHRNA10 (25% identical), CHRNA2 (25% identical), CHRNB3 (25% identical), CHRNA7 (25% identical), CHRNA9 (24% identical), CHRNA3 (24% identical), and 33 more.
Diseases named in the same sentence as HTR3A in open-access papers:
HTR3A is named in the same sentence as 95 diseases in open-access papers, as found by Europe PMC text mining. Sharing a sentence is not in itself a finding about the gene and the disease. The quoted sentences say what the papers report.
Anxiety (29 papers, 2011 to 2026). Intense feelings of nervousness, tension, or panic often arise in response to interpersonal stresses. "The Htr3a gene and serotonin have been linked to anxiety and moods as well as psychoses, and interactions with 5HT3 receptors are also involved with aggressive behavior, depression, and the stress response." (PMID 25165739, 2014). "Specificity protein 2 (Sp2, rs3708840), tryptophan hydroxylase 1 (Tph1, rs262731280) and serotonin receptor 3A (Htr3a, rs50670893) were associated with activity/anxiety behaviours, and microtubule-associated protein 2 (Map2, rs13475902) was associated with cognitive performance." (PMID 28145470, 2017). "We report a strong decrease of HTR3A expression one hour after the peak of anxiety, compatible with a regulation through DNAm." (PMID 35105872, 2022). "In the prefrontal cortex, Sig1R KO mice had significantly higher expression of the gene Htr3a, which modulates depression- and anxiety-related behaviors." (PMID 35884876, 2022). "Amygdalar genes that were changed across treatment groups also were related to psychological conditions such as depression (Drd2), stress enhanced fear learning (Gabra4), chronic mild stress (Drd1a), and anxiety, mood disorders, and psychoses (Htr3a)." (PMID 25165739, 2014). "Downregulation of Slc18a1, Cacna1s, and Htr3a gene expression may be aimed at suppressing the manifestation of anxiety-related traits in ISIAH rats." (PMID 40806189, 2025). "In fact, HTR3A rs1062613 had initially been associated with conditions seen in IBS-like depression and anxiety, and had also been correlated with the severity of IBS symptoms and anxiety." (PMID 36121467, 2022). "To date, the decreased expression of Htr3a may explain, at least in part, the changed cognitive and anxiety behaviors in Np65-KO mice." (PMID 29974341, 2018).
depression (20 papers, 2011 to 2025). "Furthermore, Htr3a and Htr3b gene-related polymorphisms are associated with genetic predisposition to musculoskeletal pain, depression disorders, and increased psychological conditions of dementia in patients with AD." (PMID 39329756, 2024). "Taken together these findings indicate that genetic variants in the HTR3A and HTR3B may be involved in the pathophysiology of depressive disorders and the clinical effect of 5-HT3 antagonists." (PMID 28002447, 2016). "Focusing on the serotonergic system—the foundation of the monoamine hypothesis of depression—we observed a significant reduction in 5-HT levels in the PFC following FMT, along with H3K27me3-mediated transcriptional repression of key genes including Tph2, Htr1d, Htr2a, Htr3a, Htr6, and Htr7." (PMID 41041075, 2025).
irritable bowel syndrome (12 papers, 2010 to 2022). Irritable bowel syndrome (IBS) is a chronic functional condition of the lower gastrointestinal (GI) tract characterized by abdominal pain or discomfort and disordered bowel habit (diarrhea, constipation, or fluctuation between the two). "A SNP in the HTR3A gene, c.-42C>T (C178T; rs1062613) was reported more frequent in patients with irritable bowel syndrome (IBS) compared to healthy controls." (PMID 28002447, 2016).
schizophrenia (11 papers, 2009 to 2025). A major psychotic disorder characterized by abnormalities in the perception or expression of reality. "The present paper describes the results of an association study of in the end 24 polymorphic variants of HTR1A, HTR1B, HTR2A, HTR2C, HTR3A, HTR3B, and HTR6 genes with TD and two of its subtypes in 449 patients with schizophrenia." (PMID 32390801, 2020). "A set of 29 SNPs of genes of serotonin receptors HTR1A, HTR1B, HTR2A, HTR2C, HTR3A, HTR3B, and HTR6 was studied in a population of 449 Caucasians (226 females and 223 males) with verified clinical diagnosis of schizophrenia (according to ICD-10: F20)." (PMID 32390801, 2020).
Nausea (5 papers, 2010 to 2025). A sensation of unease in the stomach together with an urge to vomit. "For instance, Htr3a+ neurons mediate toxin-induced nausea, while other vagal subsets modulate gut sympathetic tone or promote dopamine release, affecting gastrointestinal function and behavior." (PMID 40453085, 2025). "The nodose also has a high degree of enrichment for the ionotropic serotonin receptors Htr3a and Htr3b, which are the pharmacological targets of antiemetic and anti-nausea drugs such as ondansetron." (PMID 33424545, 2020). "The objective for this study was to investigate whether MTX-induced nausea was associated with selected SNPs in candidate genes encoding MTX transporter proteins (SLCO1B1, SLCO1B3, SLC19A1, ABCB1, ABCC2), the MTHFR enzyme (MTHFR) and the 5-HT3-receptor (HTR3A, HTR3B), in children with JIA." (PMID 33794950, 2021).
Pruritus (5 papers, 2016 to 2025). Pruritus is an itch or a sensation that makes a person want to scratch. "Nevertheless, there exist other potentialities as well, as research has investigated that acute and chronic itch could be induced by 5-HT; also, through HTR3A, 5-HT may activate NF-κB by triggering the specific itch-related intracellular mechanism after binding to HTR3A." (PMID 40243950, 2025).
bipolar disorder (3 papers, 2016 to 2025). A disorder of the brain that causes unusual shifts in mood, energy, activity levels and the ability to carry out day-to-day tasks. "Although several studies have reported an involvement of polymorphisms in the HTR3A (rs1062613) and HTR3B (rs1176744) genes and psychiatric conditions, such as eating and bipolar disorders, relatively few have explored their role in pain conditions." (PMID 28002447, 2016). "While HTR1A, HTR2A, and HTR7 are known targets of lurasidone, MAOB, HTR3A, SLC18A2, and HTR1B were identified for the first time as targets of lurasidone potentially involved in its associated induction of acute manic episodes in people with bipolar depression." (PMID 40202273, 2025). "This study revealed that lurasidone may regulate the serotonergic synapse signaling pathway by interacting with the identified core targets MAOB, HTR1A, HTR2A, HTR3A, SLC18A2, HTR1B, and HTR7 to induce treatment‐emergent mania in people with bipolar depression." (PMID 40202273, 2025). "Our bioinformatics and computational analyses demonstrated that lurasidone may regulate the serotonergic synapse signaling pathway by targeting proteins such as MAOB, HTR1A, HTR2A, HTR3A, SLC18A2, HTR1B, and HTR7 to induce treatment‐emergent mania in people with bipolar depression." (PMID 40202273, 2025).
dyspepsia (3 papers, 2011 to 2022). An uncomfortable, often painful feeling in the stomach, resulting from impaired digestion. "Interestingly, rs1062613 in HTR3A has also been associated with dyspepsia and hypersensitivity in gastroesophageal reflux disease, possibly due to reduced 5-HT3 receptor activity in the descending serotonergic pathway." (PMID 36121467, 2022).
esophageal squamous cell carcinoma (3 papers, 2022 to 2023). Esophageal squamous cell carcinoma (ESCC) is a type of esophageal carcinoma (EC) that can affect any part of the esophagus, but is usually located in the upper or middle third. "LINC01305 has been shown to regulate the target gene HTR3A mRNA through interaction with IGF2BP2 and IGF2BP3, thereby participating in the metastasis and proliferation of esophageal squamous cell carcinoma." (PMID 36204323, 2022). "Moreover, linc01305 increases the stability of HTR3A mRNA by interacting with IGF2BP2, thereby promoting the metastasis and proliferation of esophageal squamous cell carcinoma." (PMID 35299748, 2022).
lung adenocarcinoma (3 papers, 2016 to 2023). A carcinoma that arises from the lung and is characterized by the presence of malignant glandular epithelial cells. "Although there are no reports of HTR3A in human tongue SCC, elevated HTR3A expression correlates with increased human lung adenocarcinoma cell proliferation and is associated with aggressive histopathology." (PMID 36820942, 2023).
neuroblastoma (3 papers, 2021 to 2022). Neuroblastoma (NB) is the most common solid, extracranial childhood tumor. "While all cell lines were negative for MYCN amplification (two copies of gene in the genome), HTR3A protein expression was associated with expression of major drivers of aggressive neuroblastomas, N-MYC and c-MYC44,45, or one of the core stemness factors SOX2." (PMID 35614045, 2022). "In line with this, we demonstrate that neuroblastoma cell lines with high expression of HTR3A are more tumorigenic and respond to HTR3A agonists with reduced proliferation rate." (PMID 35614045, 2022). "To investigate the possible action of 5HT on HTR3A in the progression of tumors originating from sympathoadrenal cells, we analyzed several clones of human-derived neuroblastoma for HTR3A expression and tumorigenicity using an immunodeficient mouse model." (PMID 35614045, 2022). "Moreover, the origin of neuroblastoma is highly debatable, and our results regarding the feedback loop mechanism involving 5HT and HTR3A in “bridge” cells in vivo and in cancer cell lines should be interpreted with great care." (PMID 35614045, 2022). "In line with the in vivo cell cycle progression experiments, we managed to inhibit the proliferation rate of HTR3Ahigh neuroblastoma cells with a specific HTR3A agonist, which might be developed into a potential therapeutic strategy, especially in a combination with differentiation-inducing drugs." (PMID 35614045, 2022). "Based on mRNA and protein expression levels, the examined neuroblastoma cell lines could be characterized as either HTR3Ahigh (SH-SY5Y, CHLA-15, and CHLA-20), expressing markedly high levels of HTR3A, or HTR3Alow (NBL-28, NBL-38, and NBL-40), with only weak HTR3A expression." (PMID 35614045, 2022). "Of interest, only the Htr2a and Htr3a genes were significantly expressed (i.e., RPKM > 50) in N2A mouse neuroblastoma cells, and expression of Htr2a was not altered following exposure to TBI and/or DM autoantibodies." (PMID 34013450, 2021).
breast carcinoma (2 papers, 2021 to 2023). "The genetic alteration of HTR1D, HTR3A, HTR3B, and HTR6 in breast cancer patients was significantly associated with shorter overall survival (OS)." (PMID 37795441, 2023).
fibromyalgia (2 papers, 2012 to 2016). A chronic disorder of unknown etiology characterized by pain, stiffness, and tenderness in the muscles of neck, shoulders, back, hips, arms, and legs. "One study investigated sequence variation in the HTR3A and HTR3B gene polymorphisms in fibromyalgia patients in order to reveal a possible involvement in its pathophysiology." (PMID 28002447, 2016).
mood disorder (2 papers, 2013 to 2014). A cognitive disorder a disturbance in which the person's mood is hypothesized to be the main underlying feature. "Genetic variants in genes related to serotonin transmission (e.g. HTR1B,HTR3A, HTR5A, etc) were associated with mood disorder." (PMID 23326387, 2013).
Myalgia (2 papers, 2021 to 2025). "Another study that stratified participants based on TMDp subtypes investigated polymorphisms in genes encoding serotonin receptors (HTR2A and HTR3A) and found that carriers of the minor allele experienced higher pain intensity in patients with myalgia." (PMID 40868215, 2025). "The distribution of HTR2A (rs9316233), HTR3A (rs1062613), HTR3B (rs1176744), SERT (5-HTTLPR) and COMT (rs4680) genotypes in 117 patients with TMD myalgia (16 men and 101 women)." (PMID 35047998, 2021).
rosacea (2 papers, 2019 to 2025). A chronic erythematous skin disorder that affects the face. "This study preliminarily revealed that HTR3A is the key mediator of 5-HT promoting rosacea-like inflammation, leading to novel therapeutic perspectives for rosacea." (PMID 40243950, 2025). "The redness score further demonstrated that the HTR3A antagonist TPS significantly inhibited the L5-induced rosacea-like dermatitis, while TPS itself did not cause any changes in skin manifestations." (PMID 40243950, 2025). "Additionally, the HTR3A antagonist TPS significantly inhibited rosacea-like symptoms, reversed histological changes, and reduced the mRNA expressions of cytokines in rosacea-like mice models." (PMID 40243950, 2025). "Moreover, TPS, as the selective antagonist of HTR3A, completely reversed the exacerbated L5-induced rosacea-like inflammation in THP-1-derived macrophages and mice, demonstrating that TPS have a beneficial effect on the improvement of rosacea." (PMID 40243950, 2025).
alcohol addiction (1 paper, 2022). "Besides, our result on rs1062613 in HTR3A, a functional variant widely concerned to be associated with alcohol addiction, was in accordance with previous studies reporting a negative result on OCD." (PMID 35633798, 2022).
anorexia nervosa (1 paper, 2020). A disorder most often seen in adolescent females characterized by a refusal to maintain a minimally normal body weight, an intense fear of gaining weight, a disturbance in body image, and, in postmenarcheal females, the development of amenorrhea. "A previous study reported that the Htr3a gene was associated with the restricted type of anorexia nervosa, which is characterized by strict dieting and physical activity in humans." (PMID 32029228, 2020).